NCAL1 (NK cell activity associated lncRNA 1)
Gene: Long non-coding RNA gene on chromosome 2 (87,455,476 to 87,767,359, forward strand). Ensembl gene ENSG00000284879.
Diseases named in the same sentence as NCAL1 in open-access papers:
NCAL1 is named in the same sentence as 1 disease in open-access papers, as found by Europe PMC text mining. Sharing a sentence is not in itself a finding about the gene and the disease. The quoted sentences say what the papers report.
tumor (1 paper, 2022). "Furthermore, NCAL1 enhanced the cytotoxicity of NK cells toward tumor cells through the Gab2-PI3K-AKT pathway." (PMID 36248894, 2022).